MET (MET proto-oncogene, receptor tyrosine kinase)
Diseases named in the same sentence as MET in open-access papers (continued):
Sharing a sentence is not in itself a finding about the gene and the disease.
tumor (continued). "HGF is overexpressed in 1.6–4% of GBM patients, and via activation of MET, enhances tumour growth and angiogenesis." (PMID 31616641, 2019). "EF-2 treatment showed good suppression of p-c-MET levels in tumor progression mode and impressively reduced both the total and activated c-Met levels in recurrence tumors." (PMID 31590382, 2019). "Up-regulation of c-MET expression contributes to promoting tumor progression, invasion, metastasis, and angiogenesis in different types of solid tumors, including NSCLC." (PMID 29187584, 2019). "Our data validate MET/FAK signalling as a mechanism that enables CDK4/6-independent CDK2 activation and cell cycle transit, and we provide evidence for the utility of MET or FAK inhibition as a means to improve tumour response to CDK4/6 inhibition in vivo." (PMID 31296956, 2019). "Together, these results provide evidence that MET activity constitutes a resistance mechanism in vitro and in vivo, reducing the tumour cell response to CDK4/6 inhibition." (PMID 31296956, 2019). "In summary, this study demonstrated that MET has a role in tumor immune evasion via up-regulating the expression of co-inhibitory molecules, particularly PD-L1, and down-regulating the expression of co-stimulatory molecules." (PMID 31480591, 2019). "HGF/c-MET signalling has been shown to promote tumour progression, particularly influencing tumour invasiveness and metastatic potential." (PMID 31554791, 2019). "Such a broad spectrum of HGF/c-Met actions led to the investigation of both MET gene expression and c-Met activity in tumor cells." (PMID 30909397, 2019). "In vitro, MET overexpression in tumor cells contributed to the suppression of immune cell function, which was partially restored by treatment with a MET inhibitor or PD-L1 blockade." (PMID 31480591, 2019). "Lactate functions as the signaling molecule instructing CAFs to secrete HGF, the soluble cue responsible for the induction of MET TKI resistance in tumor cells, as previously reported." (PMID 30927908, 2019). "High level of MET also correlates with poor prognosis for patients, as a result of increased tumor growth and invasion, while higher expression of this receptor in primary uveal melanoma is associated with increased risk of liver metastasis." (PMID 31649529, 2019). "Metastatic CMM tumors displayed moderate to high cytoplasmic and membranous ERBB3 and MET expression in 12/13 (92%) and 9/21 (43%) BRAF-mutated tumor samples, respectively." (PMID 31506424, 2019). "While MET contributes to tumor progression and aggressiveness by diverse mechanisms, its role in the regulation of the tumor immune response is unclear." (PMID 31480591, 2019). "HGF released from fibroblasts acts as a ligand for a tyrosine kinase receptor, MET, on neighboring tumor cells." (PMID 30631034, 2019). "We found that MLN0128 or PD901 single treatment led to slower tumor growth in AKT/c-MET mice, as demonstrated by a significant lower tumor burden than the vehicle cohort." (PMID 31277283, 2019). "The majority of studies focused only on verification if used EGFR inhibitors combined with MET inhibitors synergistically affect cell viability or tumor growth." (PMID 31649529, 2019). "HGF activates the c-MET signaling pathway, which stimulates the invasive and metastatic potential of various tumor cells." (PMID 31355133, 2019). "Meanwhile, in B16F10 melanoma, T241 fibrosarcoma, LLC, and MMTV-PyMT-derived lung adenocarcinoma, tumor-induced TNF-α stimulates the NF-kB signaling pathway to express proto-oncogene MET in neutrophils." (PMID 31474975, 2019). "At the molecular level, AKT/c-MET tumor cells demonstrated high levels of activation of the AKT/mTOR and Ras/MAPK cascades." (PMID 31277283, 2019). "Stromal cells, integral components of the tumor microenvironment, activate c-MET through HGF release." (PMID 30642077, 2019). "Studies on dual blockade of EGFR and c-MET have reported promising anti-tumor activity of combined treatment." (PMID 31308358, 2019).
tumor (continued). "Tumor growth was monitored in AKT/c-MET mice until 4 weeks after injection, when the mice display a moderate tumor burden (average liver weight ~4 g)." (PMID 31277283, 2019). "c-MET dysregulation can trigger aggressive proliferation and activation mechanisms of quiescent or dormant tumor cells, repopulation, and subsequent relapse and recurrence in breast and several other cancers." (PMID 31590382, 2019). "Activation of MET promotes cell invasion and triggers metastasis by directly participating in tumor angiogenesis." (PMID 31569444, 2019). "Here, in vitro, BsAb-5 inhibits HGF-mediated tumor development, including proliferation, migration, and apoptosis, serving as an inhibitory c-MET antibody." (PMID 29187584, 2019). "In comparison with the results obtained in non-tumor tissue samples, c-MET was overexpressed in 91.3 % of tumor tissues (p < 0.01)." (PMID 30850583, 2019). "This is supported by a study from Italy that found that KRAS mutations and HER2/MET amplifications were the most common resistance mechanisms detected in ctDNA and tumor tissue analysis, and that patients with MET amplification had a shorter PFS." (PMID 31824558, 2019). "MET inhibitors have shown promising antitumor activities in preclinical and early phase clinical trials of several tumor types, although the results of most phase III trials with these agents have been less encouraging." (PMID 31832192, 2019). "Whereas, cancer cell lines knocked down for c-MET had a slower tumor growth rate in mice, the addition of capmatinib countered the therapeutic effect of c-MET knockdown, suggesting that TME-expressing c-MET were involved in the anti-tumor response." (PMID 31616408, 2019). "In previous clinical trials, high c-MET expression was described as an incidental biomarker of tumor sensitivity to the anti-tumor activity of Tivantinib38,41." (PMID 30850583, 2019). "In the analyzed tumor cells, the expression of genes involved in the immune response was significantly changed, as was that of genes possibly regulated by MET." (PMID 31480591, 2019). "Expression of MET or MTOR was significantly higher in tumor tissues than in normal pleura in 66/92 (71.7%) and 46/95 (48.4%) MPM, respectively." (PMID 29755689, 2018). "Xenograft studies with MET amplified gastric tumor cells showed significant tumor growth inhibition because of antiproliferative and proapoptotic effects of the drug and down regulation of PI3K/AKT and RAS/MAPK pathways." (PMID 30134579, 2018). "On the one hand, MSC2156119J effectively inhibits c-MET-positive HCC tumor growth, and also diminished the number of metastatic foci of lung." (PMID 30360560, 2018). "Given the recent breakthrough in cancer immunotherapy, understanding the role of MET inhibition in tumor immunology is essential toward future improvement of MET-targeting therapeutics." (PMID 30208970, 2018). "HGF is a multifunctional growth factor reported to have an important role in tumor progression through its specific receptor tyrosine kinase MET, the c-met proto-oncogene product." (PMID 30469509, 2018). "To understand the link between c-MET signaling and Mcl-1 regulation, we focused on tumor cell metabolism." (PMID 29743557, 2018). "And MET has been found to be a tumor promoter in several types of cancer related to tumor growth, including CRC." (PMID 29581707, 2018). "HIF-1α, induced by the hypoxic microenvironment, generated during anti-angiogenic therapy stimulates β1 integrin expression, which interacts with c-MET signaling and results in an enhancement of tumor cell invasiveness." (PMID 29670046, 2018).
tumor (continued). "HGF/MET autocrine loop activity can lead to the overexpression of Bcl‐2 and mTOR, which inhibit the translation initiation factor eIF2 alpha, making the tumor cells resistant to both autophagy and apoptosis." (PMID 29282893, 2018). "MET has been found to be a tumor promoter in several types of cancer related to tumor growth, including CRC." (PMID 29581707, 2018). "Within tumor environments, VEGFR and MET signaling pathways have synergistic effects on tumor growth." (PMID 29712569, 2018). "The MET/HGF pathway is involved in the complex crosstalk between tumor and stroma, in particular in the interaction between cancer cells and activated PSCs." (PMID 30544501, 2018). "Merestinib (LY2801653) is an orally bioavailable, type II MET kinase inhibitor, with a slow binding off-rate, and has demonstrated anti-tumor and anti-angiogenic activity in several MET amplified and MET autocrine xenograft tumor models." (PMID 29188469, 2018). "MET overexpression is directly correlated to tumor grade, and likely supports the pro-metastatic role of TME by sensitizing cancer cells to HGF-driven signaling." (PMID 30544501, 2018). "The HGF/MET signaling pathway regulates a wide variety of normal cellular functions that can be subverted to support neoplasia, including cell proliferation, survival, apoptosis, scattering and motility, invasion, and angiogenesis." (PMID 29188469, 2018). "Microarray analysis of this model showed upregulation of c-Met; adding a MET inhibitor with bevacizumab treatment impeded tumor invasion and prolonged survival in resistant mice." (PMID 29560266, 2018). "The stimulation with both growth factors ensures that both signaling pathways initiated from EGFR and MET are activated, which mimics physiological conditions in the tumor micro milieu." (PMID 30227653, 2018). "Such crosstalk induces ligand-free activation of c-MET signaling and leads to increased tumor cell proliferation, survival, migration, invasion, angiogenesis, and metastasis." (PMID 30352967, 2018). "c-MET signaling in the presence of its ligand HGF controls tumor growth and invasiveness by activating MAPK/ERK cascades, PI3K/Akt axis, STAT3 pathway, and/or NF-κB inhibitor-α kinase (IKK)—NF-κB complex." (PMID 29670046, 2018). "Emerging evidences suggest that the promoting effect on cancer metastasis caused by angiogenesis inhibition is due to the hypoxia, and tumor vascular pruning resulted from the inhibition of VEGF pathway triggers upregulation of MET expression." (PMID 29712569, 2018). "Transfection of bone marrow stromal cells with miR-340 generates exosomes capable of inhibiting tumor angiogenesis via the HGF/c-MET signaling pathway in endothelial cells." (PMID 30018618, 2018). "C-MET is a protein, encoded by MET oncogene, possesses tyrosine kinase activity involved in tumour development and metastasis." (PMID 30069430, 2018). "Another study demonstrated high levels of MET amplification seen in tumor biopsies of a mutant T790M EGFR NSCLC patient following osimertinib treatment." (PMID 29973561, 2018). "A mouse model engineered to conditionally express PIK3CA (H1047R) has revealed that focal amplification of either MET or c-MYC was present in tumours which reoccurred after PIK3CA inactivation." (PMID 29374181, 2018). "Compound 238 demonstrated effective tumor growth inhibition in c-MET dependent tumor models with good oral PK properties and an acceptable safety profile in preclinical studies." (PMID 29329257, 2018). "Forced expression of miR-27b suppressed DLBCL cell proliferation and tumor growth via repressing PI3K/AKT pathway by targeting MET." (PMID 30021600, 2018).
tumor (continued). "Bivalent antibodies have shown promising potential as biological therapeutics capable of inhibiting tumor growth driven by elevated HGF as well as by constitutive activation of c-MET through overexpression, gene amplification, or genetic mutation." (PMID 29725606, 2018). "Here, we highlight the role of TGFβ1 as inducer of tumor cell migration by increasing HGF/MET signaling in vitro." (PMID 30004628, 2018). "Our study found that the increased expression of HGF in CAFs induced by MET-unamplified GC contributed to the malignant phenotype of both MET-unamplified GC and CAFs in tumor microenvironment." (PMID 30158543, 2018). "In three paired randomly-selected tissue samples, MET protein levels were increased in cancer tissues, compared to those in non-tumor tissue samples." (PMID 30463570, 2018). "This is the first preclinical study reporting the evaluation of a MET-targeting kinase inhibitor in combination with an anti-MET antibody in a tumor model bearing MET exon 14 skipping." (PMID 29188469, 2018). "In vivo anti-tumor effect in the Hs746t xenograft model with the MET-targeting antibody and kinase inhibitors reflects the same trend as the in vitro data in this MET exon 14 skipping cancer model." (PMID 29188469, 2018). "The in vivo and in vitro data in this study consistently demonstrate that MET kinase inhibitors such as merestinib and crizotinib result in better anti-tumor response in the MET exon 14 skipping Hs746t model than the anti-MET antibody emibetuzumab." (PMID 29188469, 2018). "The efficacy of nonclinical studies showed that tepotinib was a promising therapeutic drug in c-MET-positive HCC tumor." (PMID 30360560, 2018). "HGF and c-MET usually mediate heterotypic cell–cell interactions, such as epithelial–mesenchymal, including tumor–stroma interactions." (PMID 30513872, 2018). "The CD44v6 peptide inhibited c-MET phosphorylation in the primary tumor and HGF and VEGF secretion in L3.6pl cells." (PMID 29747682, 2018). "The activation of the HGF/MET signaling axis is reported to be involved in tumor progression, including increased cell-proliferation, motility, invasiveness (epithelial-mesenchymal transition: EMT) and anti-apoptotic potential." (PMID 30469509, 2018). "Activation of the c-MET pathway promotes tumor cell growth, angiogenesis, and metastasis, leading to more aggressive forms of HCC and poor outcomes." (PMID 29558905, 2018). "Immunohistochemical analysis revealed significantly enhanced phosphorylation of MET in bone metastasis compared with subcutaneous implanted tumor cells." (PMID 29890660, 2018). "Tivantinib (ARQ 197) and cabozantinib are MET inhibitors that act by binding to its dephosphorylated state which is responsible for inhibition of growth and apoptosis in human tumour cell line." (PMID 30069430, 2018). "We, therefore, focused our attention on determining the effects of macrophages treated with exosomes containing activated MET on GC malignancy and tumour progression." (PMID 30160350, 2018). "The receptor is upregulated in cancer, and both c-MET and s-MET have been investigated as biomarkers of malignancy, metastasis and tumor progression." (PMID 30237882, 2018). "Immunocompetent orthotopic mice model of hepal-6 was established to investigate the effects of either VEGF antibody alone or in combination with the selective MET inhibitor on tumor aggressiveness." (PMID 29712569, 2018). "Recent studies showed that mice with reduced levels of matriptase display a significant delay in mammary tumor formation and blunted tumor growth mediated through the HGF/MET axis." (PMID 29899836, 2018). "As a correlative study, MET copy number analysis and the presence of the EGFR mutation were determined in these 58 tumor samples." (PMID 29416799, 2018). "Other genes, especially MET, involved in the carcinogenesis of a number of tumors, were also found to be determinants for tumor progression and resistance to treatments." (PMID 30474572, 2018).
tumor (continued). "In such conditions, the HGF secreted by the reactive tumor stroma acts on cancer cells expressing MET to promote pro-invasive and anti-apoptotic responses." (PMID 30544501, 2018). "Several studies reported that high-c-Met expression tumor cells due to copy number alteration of proto-oncogene MET showed no responses to the stimulation of their ligands, while the opposites remained." (PMID 30158543, 2018). "Two researchers have suggested that ectopic expression of miR-34a was related to tumor metastasis and invasion via modulating c-MET signaling pathway." (PMID 29298665, 2018). "Selective VEGF signaling inhibition by VEGF antibody significantly reduced in vivo tumor growth of the orthotopic mice models, simultaneously also enhanced tumor invasion and metastasis, but inhibiting MET signaling attenuated this side-effect." (PMID 29712569, 2018). "These experimental results have demonstrated the significance of c-MET and PDGFRα signalling for growth and/or survival of SS tumours." (PMID 28511645, 2017). "MET overexpression (IHC 3+) was more common in cases with deeper infiltrating tumor and advanced clinical stages." (PMID 28052014, 2017). "We demonstrated that HGF, commonly overexpressed in the tumor microenvironment, confers resistance to MET- targeted therapy in MET-amplified NSCLC cells." (PMID 28968967, 2017). "Double staining of TGF-β2 and p-c-MET allowed the classification of the tumor specimens into four groups." (PMID 29238047, 2017). "For our routine practice, we have thus used a diagnosis strategy combining two techniques suitable for FFPE tumor biopsy genetic testing with a high sensitivity and specificity, enabling us to detect all gene abnormalities leading to MET exon 14 splicing." (PMID 28418914, 2017). "The tyrosine kinase c-MET acts as a tumor suppressor in NSCLC, and as a resistance mediator to erlotinib in EGFR-activating mutations." (PMID 29156837, 2017). "Patient #2's tumor initially harbored a very focal, high level amplification of the MET proto-oncogene." (PMID 28903445, 2017). "Taken together, MET-induced PD-L1 ultimately leads to tumor progression and metastatic potential by an oncogenic pathway and by interrupting anti-tumor immunity." (PMID 29137273, 2017). "The growth and motility factor Hepatocyte Growth Factor/Scatter Factor (HGF/SF) and its receptor, the product of the MET proto-oncogene, promote invasion and metastasis of tumor cells and have been considered potential targets for cancer therapy." (PMID 28827556, 2017). "The proto-oncogene MET is a receptor tyrosine kinase that can promote tumor development and progression." (PMID 27844328, 2017). "SRI31215 blocked crosstalk between tumor cells and fibroblasts and overcame fibroblast-mediated resistance to MET inhibition by preventing fibroblast-mediated reactivation of AKT and ERK signaling." (PMID 28968967, 2017). "The HGF/c-MET signal pathway plays a significant role in tumor development and metastasis, often through activation of downstream molecules, including AKT and ERK1/2 pathways." (PMID 28404966, 2017). "In the remaining 2 patients, the T790M mutation was detected in circulating free DNA in one case and in a tumor biopsy obtained before the re-biopsy displaying MET overexpression and MET amplification in another case." (PMID 29285237, 2017). "Although patients with MET-high tumor tended to show better survival, further studies to explore more specific biomarkers are warranted to identify ideal candidates for MET inhibitors in NSCLC." (PMID 29088885, 2017). "Various studies agree that HGF/MET signaling promotes biological activities, resulting in tumor growth, angiogenesis, and the development of invasive phenotypes, making this receptor an attractive target for potential anticancer treatment." (PMID 28960893, 2017). "In vivo tumor models harboring PIK3CAH1047R are equally more resistant to MET inhibition than their wild-type counterpart." (PMID 28532501, 2017).